MRGPRG (MAS related GPR family member G)
Description:
Orphan receptor. May regulate nociceptor function and/or development, including the sensation or modulation of pain (By similarity).
Synonyms: GPR169; MRGG
Tractability: Small molecule: it belongs to a druggable protein family. Antibody: UniProt places it where antibodies can reach, with medium confidence; UniProt predicts a signal peptide or a membrane-spanning region; its Gene Ontology location is reachable by antibodies, with medium confidence.
Target class: Family A G protein-coupled receptor; Membrane receptor
Gene: Protein-coding gene on chromosome 11 (3,217,944 to 3,218,813, reverse strand). Ensembl gene ENSG00000182170.
Subcellular location: Cell membrane
Gene Ontology:
Molecular function: G protein-coupled receptor activity
Biological process: G protein-coupled receptor signaling pathway; adenylate cyclase-modulating G protein-coupled receptor signaling pathway
Cellular component: plasma membrane; membrane
Genetic constraint (gnomAD): Missense variants: 395 observed, 375.26 expected, observed/expected ratio (o/e) 1.05, 90% interval 0.97 to 1.14. Synonymous variants: 216 observed, 190.11 expected, observed/expected ratio (o/e) 1.14, 90% interval 1.02 to 1.27.
Homologues: Orthologues: chimpanzee MRGPRG (98% identical), macaque MRGPRG (89% identical), dog MRGPRG (67% identical), mouse Mrgprg (57% identical), rat Mrgprg (57% identical), rat Mrgprgl1 (53% identical). Paralogues in human: MRGPRE (37% identical), MRGPRX1 (34% identical), MRGPRD (34% identical), MRGPRF (34% identical), MRGPRX4 (33% identical), MRGPRX2 (32% identical), MRGPRX3 (31% identical), MAS1L (26% identical), MAS1 (24% identical), GPR152 (22% identical).